GPI (glucose-6-phosphate isomerase)
Diseases named in the same sentence as GPI in open-access papers (continued):
Sharing a sentence is not in itself a finding about the gene and the disease.
prostate carcinoma (3 papers, 2016 to 2023). A carcinoma that arises from epithelial cells of the prostate gland. "For example, glucose-6-phosphate isomerase (GPI) expression is increased in prostate cancer cells exposed to acute cycles of hypoxia (1% oxygen) in an androgen-depleted environment." (PMID 37020039, 2023). "We find that five of these genes (IRF2BP2, EDARADD, GPI, HMOX1, KIF3C) were over-expressed in patient samples, and the overexpression was significantly associated with prostate cancer relapse (the onset of metastatic disease) as individual and as a group." (PMID 30478344, 2018). "In the prostate cancer TCGA dataset, the overexpression of GPI occurred to ~4% of patients, and was significantly associated with shorter relapse-free survival." (PMID 30478344, 2018). "Among the glycolytic genes, we found the down-regulation of MPC1 (BRP44L), and the up-regulation of HK2 and GPI in prostate cancer, which also showed similar dysregulation patterns in other types of cancers." (PMID 26895100, 2016).
Apathy (2 papers, 2013 to 2021). Apathy is a quantitative reduction of interest, motivation and the initiation and persistence of goal-directed behavior, where often the accompanying emotions, thoughts, and social interactions are also diminished. "We used novel probes of oculomotor decision-making to demonstrate relative insensitivity to reward in an individual with apathy following bilateral GPi lesions." (PMID 22721958, 2013).
asthma (2 papers, 2017 to 2023). "Moreover, the differentially co-expressed genes, both up- and down-regulated in EA, were previously linked to asthma in the genome- (e.g., MRPL14, ASB3, RHOBTB2) and epigenome-wide (e.g., CLC, EPS15, GPI, SRCRB4D, STRN4) association studies." (PMID 36835202, 2023). "Among the differentially co-expressed genes, eight were previously linked to asthma in genome- (MRPL14, ASB3, RHOBTB2) and epigenome-wide (CLC, EPS15, GPI, SSCRB4, STRN4) association studies and five were mentioned in the literature in the context of asthma (SLC19A1, MAEA, CLC, ATP1B1, and RECK)." (PMID 36835202, 2023).
cryptosporidiosis (2 papers, 2021 to 2024). Intestinal infection with organisms of the genus Cryptosporidium. "Previous studies have highlighted the importance of glycolytic enzymes such as glucose-6-phosphate isomerase (CpGPI) and hexokinase (CpHK) as potential drug targets for the treatment of cryptosporidiosis." (PMID 35046922, 2021). "Therefore, the glycolytic enzymes can be the target to inhibit the growth and survival of Cryptosporidium, as the significance of glycolytic enzymes like hexokinase (CpHK) and glucose-6-phosphate isomerase (CpGPI) make them options to treat the cryptosporidiosis." (PMID 38255695, 2024).
generalized dystonia (2 papers, 2018 to 2026). "The observed shortening of the MEP onset latency could potentially be a consequence of muscle pre-activation by underlying dystonic activity of the hand muscles especially in patients with generalized dystonia, which may decrease with the GPi DBS ON." (PMID 30464181, 2018).
hereditary nonspherocytic hemolytic anemia (2 papers, 2024 to 2025). "Glucose-6-Phosphate Isomerase (GPI) deficiency is recognized as an uncommon etiology of hereditary nonspherocytic hemolytic anemia (HNSHA)." (PMID 41250704, 2025). "Glucose-6-phosphate isomerase deficiency is a rare genetic disorder causing hereditary nonspherocytic hemolytic anemia." (PMID 38539245, 2024). "Glucose-6-Phosphate Isomerase (GPI) deficiency constitutes a rare autosomal recessive enzymopathy that causes hereditary nonspherocytic hemolytic anemia (HNSHA)." (PMID 41250704, 2025).
Huntington disease (2 papers, 2019 to 2021). Huntington disease (HD) is a rare neurodegenerative disorder of the central nervous system characterized by unwanted choreatic movements, behavioral and psychiatric disturbances and dementia. "Combined stimulation of GPi and GPe is currently being explored for treating Huntington's disease to reduce the amount of choreatic movements and cognitive decline." (PMID 30862663, 2019).
lymphoma (2 papers, 2008 to 2021). A malignant (clonal) proliferation of B- lymphocytes or T- lymphocytes which involves the lymph nodes, bone marrow and/or extranodal sites. "Alemtuzumab is a mAb approved for clinical use that binds CD52, which is a GPI-anchored glycoprotein expressed on the surface of lymphoma cells." (PMID 18366248, 2008).
multiple myeloma (2 papers, 2021 to 2024). "Among all dysregulated immune-related mRNAs, AEN, CD320, FABP5, and GPI were risk factors for multiple myeloma, while CXCL12, IGKC, NOD2, VCAM1, and WNT5A were protective factors for multiple myeloma." (PMID 34249967, 2021).
pancreatic cancer (2 papers, 2002 to 2018). "PDCD4, GPI, and BHLHE4 are proteins with a described role in pancreatic cancer and, consequently, information about factors that can modulate their expression is important." (PMID 29464088, 2018).
Parkinsonian tremor (2 papers, 2018 to 2025). "In the case of Parkinsonian tremor, GPi and the basal ganglia circuitry is already seen as a ‘switch’ that may influence the cerebello-thalamo-cortical circuit indirectly through polysynaptic pathways." (PMID 40404653, 2025).
paroxysmal nocturnal hemoglobinuria (2 papers, 2021 to 2025). Paroxysmal nocturnal hemoglobinuria (PNH) is an acquired clonal hematopoietic stem cell disorder characterized by corpuscular hemolytic anemia, bone marrow failure and frequent thrombotic events. "Paroxysmal nocturnal hemoglobinuria (PNH) is an acquired clonal disorder characterized by a defect in the glycosylphosphatidyl-inositol (GPI) anchor protein, which results in partial or complete absence of GPI-linked proteins." (PMID 34057336, 2021).
polyarthritis (2 papers, 2008 to 2014). "K/BxN mice display a spontaneous and progressive polyarthritis, with persistence of high-titer autoantibodies, mainly anti–glucose-6-phosphate isomerase, in the serum." (PMID 25048575, 2014).
absence seizures (1 paper, 2014). "It is thus reasonable to infer that the activation level of GPi might serve a similar bidirectional role in modulating the absence seizures." (PMID 24626189, 2014).
bacteremia (1 paper, 2024). "Altamirano and co-workers (2021) also observed that the loss of locus K (deletions in the gtr29 gene, which encodes glycosyltransferase, and in the gpi gene encoding the enzyme glucose-6-phosphate isomerase were studied) resulted in decreased fitness in a mouse model of bacteremia." (PMID 39596757, 2024).
blepharospasm (1 paper, 2024). "GPi DBS for both tics and blepharospasm (Meige syndrome) has been reported, but there are very few reports on targeting the anteromedial part of the GPi or centromedian thalamic nucleus for blepharospasm." (PMID 38249547, 2024).
Cerebral atrophy (1 paper, 2025). Atrophy (wasting, decrease in size of cells or tissue) affecting the cerebrum. "The abnormalities that were observed were GPi mineralization and cerebral atrophy, primarily reported from the European cohort." (PMID 40655316, 2025).
dental caries (1 paper, 2018). The decay of a tooth, in which it becomes softened, discolored, and/or porous. "As a result of MRM, 14 age-specific proteins were verified to be associated with dental caries, among which glutathione S-transferase P, peroxiredoxin-6, WD repeat-containing protein 1, and glucose-6-phosphate isomerase exhibited complex interactions with each other." (PMID 30359274, 2018).
dental fluorosis (1 paper, 2022). A condition that results from excessive fluoride ingestion during tooth development, resulting in tooth discoloration ranging from white streaks to brown stains and cracks or pits in the tooth enamel. "The KGML network diagram showed that the proteins (LDHA, ENO3, GPI, and TPI1) enriched in the HIF-1 and glycolysis/gluconeogenesis pathways have a direct correlation with the formation of dental fluorosis." (PMID 35897842, 2022). "The up-regulation of ENO3, LDHA, TPI1, and GPI implies that the HIF-1 pathway and glycolysis/gluconeogenesis pathway are strengthened in ameloblasts, which affects the energy harvesting of ameloblasts and leads to the formation of dental fluorosis." (PMID 35897842, 2022).
developmental delay (1 paper, 2017). "Alternatively, individuals with variants in other GPI genes might not present with developmental delay." (PMID 28327575, 2017).
Dysarthria (1 paper, 2021). Dysarthric speech is a general description referring to a neurological speech disorder characterized by poor articulation. "Dysarthria, which is the most common GPi stimulation‐induced adverse effect, was also the most commonly reported side effect after DBS was switched back on in the present study." (PMID 33816670, 2021).
epilepsy (1 paper, 2021). A brain disorder characterized by episodes of abnormally increased neuronal discharge resulting in transient episodes of sensory or motor neurological dysfunction, or psychic dysfunction. "Our results indicate that ANT‐DBS downregulated overactivated GPi activity and exerted neuroprotective effects in the dorsal striatum, which may be associated with enhancement of the antiepileptic function of the basal ganglia that is dysfunctional in epilepsy." (PMID 33085171, 2021). "Therefore, inhibition of the GPi might also be involved in the mechanism underlying the effect of ANT‐DBS, which suggests that stimulating the GPi may be a treatment option for epilepsy." (PMID 33085171, 2021).
glioma (1 paper, 2023). A benign or malignant brain and spinal cord tumor that arises from glial cells (astrocytes, oligodendrocytes, ependymal cells). "Some glycolytic enzymes have been associated with bad prognosis; for example, glucose-6-phosphate isomerase (G6PI), which is induced by hypoxia in glioma cells." (PMID 38139462, 2023).
kernicterus (1 paper, 2016). A term used pathologically to describe BILIRUBIN staining of the BASAL GANGLIA; BRAIN STEM; and CEREBELLUM and clinically to describe a syndrome associated with HYPERBILIRUBINEMIA. "Subdivision of the secondary static patients by aetiology revealed further differences: perinatal-onset patients, particularly the Term HIE and kernicterus groups, had significantly lower GPi firing rates than those with later onset." (PMID 26848170, 2016).
leukaemia (1 paper, 2016). "Thus, in addition to enzymatic GPI, the Gpi1 gene encodes the neurotrophic factor, neuroleukin, NK, the autocrine motility factor, AMF and the maturation factor, MF, which is capable of mediating differentiation of leukaemia cells to monocytes." (PMID 27103217, 2016).
mastitis (1 paper, 2022). Inflammation of breast tissue during lactation or postpartum due to an obstructed duct or infection. "When mastitis developed (T1/C1), GPI, TPI1, GAPDH, PGK1, PGAM1, ENO1, and PKM in the glycolysis/gluconeogenesis pathway were upregulated, which promoted pyruvate synthesis with large amounts of ATP production." (PMID 36335251, 2022).
microcephaly (1 paper, 2023). A congenital or acquired developmental disorder in which the circumference of the head is smaller than normal for the person's age and sex. "Some functional studies refuted pathogenicity of apparently good candidate variants, one notable example being a PIGA variant, p.(Lys78Glu) in a patient with microcephaly which did not affect cell-surface expression of GPI-anchored proteins and is classified as likely benign (SCV000891722.1)." (PMID 37946251, 2023).
myocardial ischemia (1 paper, 2012). A disorder of cardiac function caused by insufficient blood flow to the muscle tissue of the heart. "Among them, four glycolytic enzymes, L-LDH, GAPDH, GPI, PGAM2, and two targets of MMP, gelsolin and isoform 8 of titin, are significantly released into the effluent during myocardial ischemia." (PMID 22443514, 2012).
orthostatic hypotension (1 paper, 2023). Sudden fall of the blood pressure of at least 20/10 mm Hg when a person stands up. "The GPi was not the best target in our patient, as it would not have allowed us to reduce levodopa doses and therefore orthostatic hypotension would have persisted." (PMID 38145277, 2023).
T-cell lymphoma (1 paper, 2025). "Conversely, in NK/T-cell lymphoma, SIRT5 functions as a tumor suppressor by desuccinylation and destabilization of glucose-6-phosphate isomerase (GPI), thereby inhibiting glycolytic flux and tumor growth." (PMID 41425553, 2025).
Torticollis (1 paper, 2019). Involuntary contractions of the neck musculature resulting in an abnormal posture of or abnormal movements of the head. "A future avenue that may prove useful for exploration, potentially via simulation, is whether asymmetries in GPi output can arise from upstream striatal plasticity abnormalities, as asymmetric GPi firing rates have been shown to correlate with the severity and direction of torticollis." (PMID 30955204, 2019).
triple-negative breast carcinoma (1 paper, 2026). An invasive breast carcinoma which is negative for expression of estrogen receptor (ER), progesterone receptor (PR), and human epidermal growth factor receptor 2 (HER2). "In triple-negative breast cancer (TNBC), knockdown of YBX1 inhibited the expression of glycolytic genes (ENO1, SLC2A6, LDHA, PFKP, PGAM1, and GPI) and downregulated the expression of EMT-related genes and tumor migration and invasion." (PMID 41507134, 2026).
tumor (74 papers, 1988 to 2026). "High plasma GPI expression was positively correlated with poor progression, and elevated GPI expression in tumor tissues was associated with vascular anomalies." (PMID 38573114, 2024). "In contrast to loss of the tumor-suppressive functions of CNDP2, we note that Glucose-6-phosphate isomerase (GPI) expression is associated with increased risk of progression." (PMID 41134301, 2025). "Numerous enzymes involved in glucose metabolism also play a role in tumor progression, including glucose-6-phosphate isomerase, which can inhibit apoptosis and promote tumorigenesis through PI3K/AKT activation." (PMID 36982249, 2023). "To explore the correlation between the expression level of GPI and tumor immune response, we investigated immune infiltration in BRCA with different GPI expression levels." (PMID 36246907, 2022). "To explore the expression level of GPI in normal and tumor tissues, we used the Oncomine database to analyze the expression levels of GPI mRNA in different tumors and normal tissues." (PMID 34912709, 2021). "Another notable cluster 2-selective gene related to innate immunity in the epithelium is GPI/AMF (glucose-6-phosphate isomerase/autocrine motility factor), a tumor-secreted cytokine implicated in EMT, migration, and metastasis 41,42." (PMID 30181541, 2018). "Here, we report that GAPDH is associated with glucose-6-phosphate isomerase (GPI) and pyruvate kinase M2 (PKM2) in Ehrlich ascites carcinoma (EAC) cells and also in 3-methylcholanthrene (3MC) induced mouse tumor tissue." (PMID 26911935, 2016). "Intra-tumor vaccination with TA-CIN or TA-CIN/GPI-0100 significantly inhibited TC-1 tumor growth compared to cisplatin or cisplatin plus GPI-0100 treatment." (PMID 25560237, 2015). "In contrast, mice vaccinated with TA-CIN/GPI-0100 greatly inhibited tumor growth when compared to TA-CIN or GPI-0100 alone treated mice, and the response was similar in the fresh and frozen/thawed formulations." (PMID 25560237, 2015). "Mice treated with TA-CIN/GPI-0100 vaccination exhibited robust E7-specific CD8+ T cell responses, which were associated with reduced tumor burden in the lung, whereas mice receiving either component alone were similar to controls." (PMID 25560237, 2015). "We now know that GPI/AMF is involved in tumor cell migration, invasion and angiogenesis, and that it mediates its biological effects through the interaction with its surface receptor (AMFR/gp78)." (PMID 25945836, 2015). "Additionally, 1357 proteins were identified in TV and some of them were bio-active proteins such as glucose-6-phosphate isomerase, catalase, and lysozyme C-1, which had catalytic, antioxidant, antimicrobial, and anti-tumor activities." (PMID 38535825, 2024). "Glycolysis is accomplished through a series of enzymatic reactions in the cytoplasm, and the increased expression and activity of its associated enzymes are essential in tumor cells, among which GPD2, GPI, Hsp90α and PGK2 are involved in promoting glycolysis and cancer cell proliferation." (PMID 39509399, 2024). "Therefore, we further evaluated the GPI mRNA expression pattern in A549 tumor cells by qRT-PCR and found that circadian GPI expression was consistent with that in tumor tissues." (PMID 37924048, 2023). "Moreover, compared to the control, TRF evoked the same change in GPI protein levels in A549 cells as in tumor tissues." (PMID 37924048, 2023). "To further explore the role of the RP11-620J15.3/miR-326/GPI axis in tumor growth in vivo, we subcutaneously injected HCC-LM3 cell lines transfected with miR-326 inhibitors or plasmids containing GPI mRNA that stably knocked out RP11-620J15.3 into BALB/c nude mice." (PMID 37020316, 2023). "Panel 3 indicates that GAPDH is immunoprecipitated specifically by GAPDH antibody, but not by mouse IgG, suggesting that both PKM2 and GPI are associated with GAPDH in tumor but not in normal tissue." (PMID 26911935, 2016).